INS (insulin)
Diseases named in the same sentence as INS in open-access papers (continued):
Sharing a sentence is not in itself a finding about the gene and the disease.
chronic kidney disease (continued). "Other than secondary oral drug failure and chronic renal failure, availability of new oral hypoglycemic agents, perceived risk of tight diabetic control, acceptability and practicability of insulin injection, all affect one’s decision on prescribing insulin to a patient." (PMID 28036365, 2016). "For instance, bicarbonate supplementation in diabetic patients with chronic kidney disease has shown promising results, including improved insulin resistance, serum glucose, serum insulin, and HbA1c." (PMID 41378230, 2025). "Factors associated with low SGLT2i use included older age, the presence of comorbid chronic kidney disease, concurrent use of DPP4i and insulin, and receiving prescriptions from other internists and other physicians." (PMID 40589143, 2025). "Chronic renal failure impairs gluconeogenic pathways, reduces renal clearance of insulin, impairs insulin degradation due to uremia, increases glucose uptake by red blood cells during hemodialysis, and diminishes counter-regulatory hormonal responses." (PMID 41234224, 2025). "Given that chronic renal failure can delay insulin clearance, altered insulin pharmacokinetics was initially considered." (PMID 41234224, 2025). "The shares of patients treated with insulin, oral antidiabetics or the combination align with results from a large cohort of patients with chronic kidney disease." (PMID 38493085, 2024). "Patients with VT recurrence had greater prevalence of LVH (p = 0.006), chronic kidney disease (p = 0.028), and intensive insulin therapy (p = 0.013)." (PMID 39459449, 2024). "Genetic and pharmacologic manipulation of IP6Ks in vivo and in vitro has shown their importance in metabolic disease, chronic kidney disease, insulin signaling, phosphate homeostasis, and numerous other cellular and physiologic processes." (PMID 37759717, 2023). "Acidemia has been implicated in osteopenia and osteoporosis, decreased insulin release and sensitivity, vascular-endothelial dysfunction, progression of chronic kidney disease to end-stage renal disease, cardiac arrhythmias, and heart failure." (PMID 37405134, 2023). "In the AWARD-7 trial, which included patients with T2DM and chronic kidney disease, treatment with dulaglutide compared to insulin resulted in a lower rate of GFR reduction or end-stage renal disease, particularly in those with macroalbuminuria." (PMID 36289848, 2022). "Our data demonstrate that using CGM metrics to complement HbA1c monitoring is beneficial, especially in older people, users of insulin and/or sulfonylureas, and patients with chronic kidney disease." (PMID 35908248, 2022). "At follow-up, 79% of patients were treated with insulin, 44% had chronic kidney disease stage 3–4 (CKD3–4), 21% had end-stage renal disease (ESRD), and 122 of 166 patients had renal cysts." (PMID 35480487, 2022). "Most diabetic patients on insulin have chronic kidney disease as microvascular complication of more advanced disease." (PMID 35725489, 2022). "The two patients with chronic kidney disease had blood potassium levels higher than 4.5 mEq/L during the anhepatic period, and they were treated with 10 units of regular insulin and 200 mL of 5% dextrose solution." (PMID 34943485, 2021). "Metabolic acidosis is a severe complication of chronic kidney disease (CKD) which is associated with nefarious impairments such as bone demineralization, muscle wasting, and hormonal alterations, for example, insulin resistance." (PMID 34444694, 2021). "Children with cerebral edema, chronic kidney disease and those who received pre-referral fluids and/or insulin were excluded." (PMID 34719396, 2021). "In the multivariate Cox regression model, the use of insulin for glycemic control, end-stage renal disease, previous history of amputation, previous history of endovascular therapy, and CLI were independent predictors of MALE." (PMID 32571352, 2020).
chronic kidney disease (continued). "Insulin secretion was also down-regulated in pancreatic islets cultured with urea, the concentration of which was similar to that of patients with chronic kidney disease." (PMID 32117054, 2020). "Most patients (59.2%) required insulin treatment, and half of them had chronic complications: retinopathy (57.4%), chronic kidney disease (43.8%), and cardiovascular disease (47.3%)." (PMID 32961974, 2020). "Chronic kidney disease (CKD) patients have insulin secretion disorders and resistance to insulin effects, that is responsible for the development of cardiovascular events." (PMID 30881429, 2019). "For instance, individuals with chronic kidney disease (CKD) exhibit low muscle insulin sensitivity even at the very onset of renal dysfunction." (PMID 31195596, 2019). "Determining insulin requirements for hemodialysis patients with end-stage renal disease (ESRD) is difficult." (PMID 31828166, 2019). "Predictors of carvedilol choice were chronic comorbidities and co-treatments including chronic kidney disease, human insulin, fondaparinux, strontium ranelate or recent acute episode of acute heart failure, cerebrovascular thrombosis or atrioventricular block." (PMID 31391573, 2019). "Ppard plays an important role in energy metabolism and Ppard agonist decreases insulin and glucose levels by increasing glucose transport and possibly affecting subsequent chronic kidney disease risks." (PMID 29514661, 2018). "In the light of these publications, insulin sensitivity appears to be related with chronic renal disease in those with a compromised renal function." (PMID 29855339, 2018). "Further, glucose tolerance tests indicated an increase of 25% in glycemia in chronic kidney disease rats (p<0.0001) as compared to controls whereas insulin levels remained unchanged." (PMID 28459862, 2017). "Recently, UnAG was found to preserve gastrocnemius muscle mass in male Wistar rats with chronic kidney disease (as induced via nephrectomy) by normalizing the mitochondrial reactive oxygen species production, inflammatory mediators, and insulin signaling." (PMID 29225581, 2017). "Glucose tolerance tests also indicate an increase of 25% in glycemia in chronic kidney disease rats as compared to controls, whereas insulin levels remained unchanged." (PMID 28459862, 2017). "Conversely, several studies reported that correcting overt metabolic acidosis in chronic renal failure patients with oral sodium bicarbonate improved insulin resistance." (PMID 28800090, 2017). "Patients with end-stage renal disease on hemodialysis treated with recombinant EPO have been shown to have improvement in insulin sensitivity." (PMID 27119016, 2016). "Since chronic renal disease is an insulin-resistant state, any kind of intervention that can improve insulin sensitivity in subjects with renal impairment has a theoretical potential to normalise renal dyslipidemia." (PMID 23606826, 2013). "Six patients (28.6%) were diabetic and required either insulin or oral agents, seven patients had chronic renal failure (33.3%), and two patients (9.5%) showed COPD pre-operatively." (PMID 22943887, 2012). "Both patients had a history of exogenous insulin use and chronic renal failure." (PMID 41234224, 2025). "Insulin sensitivity is influenced by various factors, including age, gender, smoking, abnormal glucose and lipid metabolism and chronic kidney diseases." (PMID 38414903, 2024). "Therefore, studies have shown that inhibition of IL-1β increases insulin sensitivity, improves renal function, and reduces cardiovascular complications in patients with chronic kidney disease." (PMID 38257150, 2024). "The higher incidence observed in our study may be due to factors such as insulin therapy and concurrent conditions like chronic renal disease." (PMID 39735099, 2024).
chronic kidney disease (continued). "Similarly, plasma C‐peptide concentrations are challenging to interpret in patients with chronic kidney disease and in the presence of anti‐insulin antibodies that bind both pro‐insulin and C‐peptide." (PMID 37035965, 2023). "In this line, estrogen supplementation in ovariectomized animals promoted insulin sensitivity, reduced inflammation and accelerated tubular cell regeneration in rats with chronic kidney disease, and reduced albuminuria, glomerulosclerosis, and hyperfiltration in a model of diabetic nephropathy." (PMID 37629165, 2023). "In addition, insulin is preferred for comorbidities such as chronic kidney disease, which can be a contraindication to oral antidiabetic drugs." (PMID 38249413, 2023). "Since insulin clearance is impaired in chronic kidney disease, SACS was performed to observe whether there was an inadequate insulin response to calcium stimulation." (PMID 37371827, 2023). "Baseline characteristics of the total population were relatively comparable between sulfonylurea and non-sulfonylurea users, except for body weight mass index (BMI), diabetic duration, chronic kidney disease, anterior infarction, and insulin (p < 0.05 for each variable)." (PMID 34124195, 2021). "Pioglitazone (PIO) is an insulin-sensitizing antidiabetic drug, which normalizes glucose and lipid metabolism but may provoke heart and liver failure and chronic kidney diseases." (PMID 34681269, 2021). "Besides, in mice of chronic kidney disease, impaired glucose-stimulated insulin secretion was observed." (PMID 32117054, 2020). "However, the associations between LA-related SNPs and other potential confounders, such as insulin sensitivity measurement and chronic kidney disease were difficult to assess, because the publicly available GWAS summary statistics are limited." (PMID 33584789, 2020). "In accordance with our findings, an important disruption in insulin release that may be associated to disorders in CRF secretion and vice-versa has already been observed in patients suffering chronic renal failure." (PMID 31191339, 2019). "The prevalences of chronic kidney disease, the proportion of insulin treatment, and the distributions of concomitant medications (other antidiabetic oral medications, antihypertensives, and lipid-lowering agents) revealed significant differences between the two groups." (PMID 31781371, 2019). "Moreover, the RAAS not only reduces blood pressure but also increases insulin sensitivity in patients with chronic kidney disease." (PMID 29844879, 2018). "Furthermore, patients with end-stage renal disease on hemodialysis treated with ESAs have been shown to have improvement in insulin sensitivity." (PMID 27119016, 2016). "We investigated the relationship of insulin sensitivity and metabolic acidosis in a subgroup of patients (diabetic patients on oral antidiabetic medications) randomized into the Use of Bicarbonate in Chronic Renal Insufficiency (UBI) study (NCT NCT01640119)." (PMID 27770799, 2016). "Therefore, in chronic renal failure, the oral agents that can be used include the insulin secretagogues repaglinide and nateglinide and the thiazolidinediones (rosiglitazone and pioglitazone), although they should be used with caution." (PMID 24427312, 2014). "Data on the effects of sodium–glucose co-transporter 2 (SGLT2) inhibitors on insulin use in people with chronic kidney disease (CKD) are limited." (PMID 40036884, 2025). "Conversely, adiponectin—an anti-inflammatory adipokine that enhances insulin sensitivity—is often reduced in chronic kidney disease (CKD)." (PMID 41150807, 2025). "We further expanded our findings to reveal that insulin resistance, lipotoxicity, and fat factor signaling pathways may all be involved in the possible mechanism linking triglycerides/high-density lipoprotein cholesterol to chronic kidney disease." (PMID 41244773, 2025).
chronic kidney disease (continued). "Disease-specific factors, including altered glucose and insulin metabolism, may apply to chronic renal failure, while other changes to patient or provider behaviors related to control or increased overall contact with a health care system may apply across different comorbidities." (PMID 37708338, 2023). "The patient had a past medical history of hypertension, chronic kidney disease (CKD), and diabetes mellitus controlled using insulin." (PMID 38264260, 2023). "Dysfunction in the musculoskeletal system is frequent in chronic kidney disease (CKD) as a result of systemic changes caused by decreased glomerular filtration rate (GFR), inflammatory process, metabolic acidosis, reduced protein intake, insulin resistance, and physical inactivity." (PMID 34519760, 2022). "Basal insulin is also an established therapy that may be an appropriate patient-centered treatment, especially for those with significantly elevated HbA1c or contraindications to alternative therapy, such as end stage renal disease." (PMID 35114955, 2022). "illustrated that patients with chronic kidney disease (CKD) have lower insulin sensitivity, decreased insulin clearance, and inadequate enhancement of insulin secretion." (PMID 36387890, 2022). "In experimental chronic kidney disease (CKD), the catabolic environment increases glucocorticoid production and suppresses insulin signaling, resulting in decreased PI3K/Akt activity." (PMID 35731367, 2022). "In chronic renal failure, protein-energy malnutrition (PEM) is frequently observed, and the presence of metabolic acidosis is assumed to be associated with PEM by generating endocrine abnormalities, such as increased protein catabolism, decreased protein synthesis, and insulin resistance." (PMID 36498702, 2022). "Moreover, increased insulin production, glomerular volume and capillary pressures have a huge further impact on the glomerular damage, creating a circulus vitiosus and leading to a chronic kidney disease." (PMID 34393633, 2021). "Furthermore, eligible patients were more frequently insulin-treated, possibly due to their poorer metabolic control (p = 0.03), and had a significantly lower prevalence of advanced heart failure, end-stage renal disease and mental or psychiatric disorders compared to NE patients (p < 0.05 for all)." (PMID 32582036, 2020). "Therefore, although circulating C-peptide concentrations are generally considered to better reflect insulin secretion than circulating insulin concentrations, this might be more complicated in circumstances of chronic kidney disease." (PMID 32957570, 2020). "Guided text entry of abstracted information might offer the advantage of greater flexibility in situations where highly variable dosing regimens may preclude generation of comprehensive pick lists (e.g., insulin regimens, immunosuppressive regi mens, adjustments of doses in chronic renal failure)." (PMID 15249262, 2004). "The gut microbiota profoundly influences metabolic regulation, affecting processes such as insulin sensitivity, lipid metabolism, and inflammation, dysregulation linked to the progression of diabetic kidney disease (DKD) and chronic kidney disease (CKD)." (PMID 40004938, 2025). "Tobacco smoking, chronic kidney disease (CKD) stage ≥3, and insulin therapy were more common among the deceased than survivors." (PMID 40378162, 2025). "Despite their overlapping characteristics, DKD differs from chronic kidney disease (CKD) owing to its unique pathophysiological mechanisms, including hyperglycemia, insulin resistance, and advanced glycation end-products." (PMID 39842843, 2025). "In T2DM patients with moderate to severe chronic kidney disease, eGFR is higher in those receiving GLP-1RAs compared to those on insulin therapy." (PMID 40699685, 2025).
chronic kidney disease (continued). "Notably, the clearance of insulin can be slowed inpatients with diabetic nephropathy/chronic kidney disease (CKD), necessitating doseadjustment of some insulin therapies, such as human insulin and IGlar, if renal functiondeteriorates, as discussed later." (PMID 38224978, 2024). "For chronic kidney disease (CKD) patients, p-cresol sulfate, which is hard to be removed by dialysis, is regarded as a uremic toxin for its potential contribution to renal and cardiovascular damages, as well as to insulin resistance." (PMID 37834066, 2023). "Many of the early studies with insulin–glucose/dextrose treatment (IDT) were performed in patients with end-stage kidney disease who were dialysis dependent or had significant chronic kidney disease (CKD)." (PMID 36417187, 2021). "The reduction of hypoglycaemic events is important in diabetic patients with chronic kidney disease (CKD), where GLP-1RAs have proven to be safe while many other antihyperglycemic drugs require dose adjustment as insulin or are simply contraindicated." (PMID 31212945, 2019). "Correspondingly, thiazolidinedione compounds (TZDs), a class of insulin-sensitizing drug used in the treatment of type 2 diabetes, and a synthetic PPARγ ligand improve glucose tolerance, which may indirectly ameliorate the progression of chronic kidney disease (CKD)." (PMID 30012954, 2018). "Thus, insulin is generally prescribed and metformin remains formally contraindicated in advanced chronic kidney disease (CKD), a late event in the course of T2DM, despite recent clinical recommendations." (PMID 28060743, 2017). "Chronic kidney disease (CKD) is marked by decrease in insulin sensitivity." (PMID 27518102, 2016). "Chronic kidney disease (CKD), which plays a critical role in the progression of end-stage renal disease, is a major obesity-related complication driven by mechanisms involving systemic inflammation, insulin resistance, glomerular hyperfiltration, and ectopic lipid deposition in renal tissues." (PMID 40777172, 2025). "A thorough workup did not reveal decompensated liver cirrhosis, chronic kidney disease, congestive heart failure, hypothyroidism, adrenal insufficiency, or insulin use." (PMID 40395710, 2025). "Gender, cause of end-stage renal disease (ESRD), dialysis method used before KTx, DGF, type of calcineurin inhibitor (tacrolimus or cyclosporin), glycaemia, HOMA and Quicki index, insulin level before KTx and BMI did not predispose to the development of DM." (PMID 38474169, 2024). "Participants with HF were also more likely to have chronic kidney disease, be on BP and lipid-lowering medications and insulin than those without HF." (PMID 38964877, 2024). "Sensitivity analyses were performed in patients without cardiovascular disease, chronic kidney disease, or insulin treatment." (PMID 38281973, 2024). "The concomitant decreased drug clearance from renal impairment in chronic kidney diseases, drug-drug interactions, and the use of insulin in combination with OADs were not examined on their impact on the results." (PMID 35078484, 2022). "Later, another study involving eight chronic renal failure (CRF) patients demonstrated that acidosis indeed contributes to the insulin resistance without affecting the action of insulin." (PMID 35807769, 2022). "Moreover, multivariate analysis including age, sex, BMI, chronic kidney disease, BNP and insulin use (Model 2) revealed that an elevated IGF-1/IGFBP-3 ratio was associated with a significantly decreased risk for CV death and 3P-MACE." (PMID 35332212, 2022). "Because of the design of the trials we were unable to assess some outcomes explored in the original study, such as time to insulin, and we did not have power to assess other outcomes, including development of end-stage renal disease." (PMID 31047901, 2019).